HIF1A (hypoxia inducible factor 1 subunit alpha)
Diseases named in the same sentence as HIF1A in open-access papers (continued):
Sharing a sentence is not in itself a finding about the gene and the disease.
tumor (continued). "HIF-1α inhibits adenosine kinase and ENTs resulting in increased accumulation of adenosine in the tumor microenvironment." (PMID 37187740, 2023). "USP28 antagonizes Fbw7-dependent HIF-1α ubiquitination and regulates tumor cell angiogenesis in an HIF-1α-dependent manner." (PMID 37190313, 2023). "HIF-1α induces the expression of vasculature endothelial growth factor (VEGF), a pro-angiogenic factor that promotes the formation of abnormal tumor vasculature characterized by a deficiency in pericytes and a leaky basement membrane." (PMID 37239368, 2023). "It has been reported that 2-methoxyestradiol downregulates HIF1α through binding to tubulin and blocking tumor interphase microtubules that are needed for HIF1α down-regulation." (PMID 37894802, 2023). "Under hypoxic conditions, HIF-1α generally plays a key role in regulating various cellular processes in tumor cells." (PMID 37626752, 2023). "The gene pathway association between these overexpressed hypoxia genes would be via the PVT1/PRC2/STAT3 pathway and the ERK/HIF-1α/p70S6K cascade, which signals tumour-induced angiogenesis." (PMID 37048688, 2023). "A cationic micellar NP combines HIF-1α siRNA and the NP-siHIF nanosystem that effectively reduced tumor cell proliferation, angiogenesis, and migration, and hindered tumor growth as well as reduced MDR1 expression both in vitro and in vivo." (PMID 36983571, 2023). "Melittin inhibited the expression of genes involved in tumor microenvironment (TME) formation via disruption of HIF-1α signaling in breast cancer (MDA-MB-231) cells." (PMID 37513529, 2023). "Nrf2 and HIF-1α are known to regulate various metabolic and proliferative pathways, which are responsible for angiogenesis, tumor proliferation and chemoresistance." (PMID 37025487, 2023). "The PI3K/Akt/mTOR signaling pathway regulates the synthesis and stabilization of HIF-1α in hypoxic tumor cells." (PMID 37227584, 2023). "Collectively, we assume that inhibition of the EGFR-HIF1a signaling pathway by EGFR-TKI administration suppressed the expression of HIF1a in the tumor, resulting in lower angiogenetic activity and leading to the lack of PTBE on imaging." (PMID 37719531, 2023). "MR16-1, a rodent analog of anti-IL-6 receptor antibody, overcame CAF-induced immunosuppression and suppressed tumor progression in immunocompetent murine cancer models by regulating HIF1α activation in vivo." (PMID 36764954, 2023). "Prior research suggests that HIF1A enhances cancer progression, spread, and metastasis by promoting angiogenesis and controlling cellular metabolism in hypoxic tumor conditions." (PMID 36816977, 2023). "In tumor tissues, HIF1α shifts glucose metabolism from oxidative phosphorylation to anaerobic processes (the Warburg effect)." (PMID 36764954, 2023). "To investigate the role of hypoxia in OSCC progression, we first analyzed HIF-1α expression in paired OSCC tumor and adjacent normal tissues." (PMID 37095487, 2023). "Although targeting HIF-1α has its challenges, modulating HIF-1α, or its downstream effectors, can be therapeutically advantageous, as shown in some pre-clinical tumor models." (PMID 36614196, 2023). "Limitations of tumor metastasis and invasiveness rests upon HIF-1α mediated transcriptional activation of matrix metalloproteinases (MMPs) and enzyme lysyl oxidase." (PMID 36891273, 2023). "In ccRCC, HIF1A is extensively studied and plays a central role in tumor development and progression." (PMID 38053655, 2023). "TIL density in the invading tumor front was inversely related with lymph node involvement (p = 0.03), HIF1α expression (p = 0.008), vessel density (p = 0.02), and MIB1 (p = 0.006)." (PMID 36586079, 2023).
tumor (continued). "Excess extracellular lactate can modulate oscillations in HIF-1α via a quorum-sensing signal, protecting tumour cells from hypoxia-induced cell-cycle arrest of division, which contributes to a more aggressive pattern of proliferation." (PMID 37233716, 2023). "Several studies have demonstrated the prognostic significance of HIF-1α overexpression in OSCC tumors, owing to its association with an advanced TNM stage, nodal involvement, increased tumor size, tumor recurrence, and poor survival." (PMID 36766555, 2023). "Previous findings suggest that hypoxia induces HIF-1α dependent lipid droplet accumulation in tumor cells." (PMID 36891273, 2023). "We also investigated the expression levels of HIF-1α and PD-L1 in tumour tissues in different groups." (PMID 37993847, 2023). "Previous studies have demonstrated that tumour hypoxia and increased HIF-1a expression promote the progression of tumours and tumour resistance to chemotherapy." (PMID 37821935, 2023). "Hypoxia fundamentally creates the low oxygen condition responsible for the alteration in Hypoxia-Inducible Factor-1alpha (HIF-1α) signaling within the tumor microenvironment, allowing tumors to survive and making them resistant to various therapies." (PMID 37492478, 2023). "Further, the oxygenation of tumor tissues in vivo was evaluated by two tumor hypoxia markers, HIF‐1α and pimonidazole." (PMID 37092578, 2023). "Patients with a poor outcome expressed PDPN broadly across the tumor microenvironment whilst HIF-1α and VEGF expression also extended into the distal stromal and immune regions and likely indicates more extensive hypoxia in this subgroup." (PMID 37350578, 2023). "Many of the metastatic phenotypes of our preclinical models were observed in clinical tumor specimens, including VHL loss resulting in the upregulation of HIF-1α and POSTN." (PMID 37069149, 2023). "It has been previously reported that stimulation of both transcription factors HIF-1α and NF-κB induces malignancy, migration, and invasion of tumor cells." (PMID 37583906, 2023). "Amphiregulin (AREG)/epidermal growth factor receptor (EGFR) signaling induces hypoxia-inducible factor-1α (HIF-1α), leading to promotion of T helper 9 (Th9) differentiation and anti-tumor functions." (PMID 36154925, 2023). "Specifically, in response to hypoxia, HIF-1α is overexpressed and/or activated and targets those genes which are required for angiogenesis, metabolic adaptation to low oxygen and promotes tumor survival." (PMID 37085672, 2023). "Under hypoxic condition, HIF-1α cannot be effectively degraded and substantially accumulates in tumor cells, and then HIF-1α binds to HIF-1β, forming a functional heterodimer, HIF-1." (PMID 37227584, 2023). "Correlations between HIF-1α expression levels and clinicopathologic variables (age, gender, Broder’s histological grade, Anneroth’s histological grade, cTNM stage, tumor size, and nodal involvement) were assessed." (PMID 36766555, 2023). "The current study elucidates the function of NF-κB in the first stages of tumour development and proliferation, when HIF-1α is inactive due to elevated pO2." (PMID 36891273, 2023). "Despite that, the study results were evaluated as preliminary proof for the suppression of HIF-1α in the tumor tissues of the patients with the use of EZN-2968." (PMID 36846589, 2023). "The inhibition of HIF-1α simultaneously suppresses the immunosuppressive activity of myeloid-derived suppressor cells (MDSCs) and improves T-cell immunity in the tumor microenvironment (TME)." (PMID 36830619, 2023). "Subsequently, hydroxylated HIF-1α is recognized by the tumor-suppressing protein von Hippel–Lindau and then polyubiquitinated for degradation by proteasomes." (PMID 37512145, 2023).
tumor (continued). "Given that HIF1α and HIF2α are master regulators of cellular response to hypoxia, we first examined their expression in thyroid tissues of normal mice and tumor tissues of BrafV600E transgenic mice by the IHC assay." (PMID 37020036, 2023). "When tumor cells are exposed to OnB in vitro, the hypoxic conditions are reversed, accompanied by the suppression of HiF-1α levels." (PMID 38063756, 2023). "On the same line, tumor-infiltrating NK cells have been described to upregulate Hif-1α in different tumor models and the genetic deletion of Hif-1α confers to NK cells superior effector functions and a more potent tumor killing." (PMID 37298470, 2023). "A previous study reported that HIF-1α increases angiogenesis, activates procancer signalling pathways, and mediates the activation of transcription factors, thereby promoting tumour progression." (PMID 37948404, 2023). "The hypoxic TME increases HIF-1α expression in tumor cells, which in turn stimulate inducible nitric oxide synthase (iNOS) and arginase (ARG1 and ARG2) synthesis." (PMID 38259478, 2023). "Factors including tumor size, age, and histological grade as well as HIF-1α, VEGF-A, and Ki67 expression, affecting the efficacy of NACT were analyzed." (PMID 37335690, 2023). "As the O2 concentration diminishes in the intermittent hypoxic and severely hypoxic zone during tumor development, HIF-1α becomes stabilized and progressively becomes transcriptionally active due to the inactivation of PHD first and FIH-1 second." (PMID 36891273, 2023). "The outcome of BACH1 stabilization following antioxidant administration — i.e., glycolysis and tumor progression — is like that of HIF1α, which is stabilized following hypoxia." (PMID 37651203, 2023). "HISLA obstructs the interaction between PHD2 and HIF-1α that leads to the accumulation of HIF-1α, which regulates glycolytic metabolism in the tumor cell." (PMID 37629204, 2023). "Recently, several studies have provided convincing evidence for a strong correlation between increased HIF-1α levels and tumour metastasis, angiogenesis, poor patient prognosis, and cancer drug resistance." (PMID 37558230, 2023). "To conclude, our study has shown significant differences in HIF-1α tissue expression levels between ccRCC and healthy kidney, with most cases having a significantly higher amount of HIF-1α in normal than in tumor tissue." (PMID 38273861, 2023). "This analysis revealed subtype-specific signatures of metabolic genes in PTC, leading to the identification of Hif-1α as one the main transcriptional contributors to the metabolic rewiring of BRAF-driven tumours." (PMID 37198319, 2023). "The HIF signaling is a key pathway for tumor cells to sense and prevail under low oxygen environment and HIF1α protein is a predominant effector in this process." (PMID 37813876, 2023). "VEGFA overexpression in the tumor represents mainly the response to increased tumor hypoxia via the hypoxia-inducible factor-1α (HIF-1α) pathway." (PMID 37893095, 2023). "While HIF-1α acts as a tumor suppressor, HIF-2α promotes oncogenic potential by driving tumor progression and metastasis through activation of hypoxia-sensitive signaling pathways and overexpression of HIF-2α target genes." (PMID 36831657, 2023). "Here, only HIF-1α + GLUT1+ neutrophils were proportionally increased in PDAC tumor tissue (23.21%) compared to adjacent matched normal tissue (8.17%), while the proportion of HIF-1α + HK2+ and GLUT1 + HK2+ neutrophils was similar between the two groups." (PMID 36614196, 2023). "HIF-1α is a transcription factor that was initially identified as an indirect marker of tumour hypoxia that responds to a decrease in oxygen levels within a cell." (PMID 37029804, 2023).
tumor (continued). "Under the hypoxia circumstances, sensors of hypoxia like hypoxia‐induced factors (HIF)‐1α enable tumor cells perceive reduced oxygen content, inducing extracellular matrix (ECM) re‐molding and epithelial‐mesenchymal transition (EMT) process subsequently." (PMID 35946175, 2023). "The in vitro evaluation was carried out based on cell viability, the impact on the macrophage population of the tumor microenvironment in co-culture conditions and the modulation of HIF-1α as an indirect indicator of oxygen consumption." (PMID 37296661, 2023). "In HCC patients, sorafenib treatment significantly increased HIF1-α expression and reduced vessel density in tumor samples." (PMID 36906597, 2023). "We have previously shown that Syk controls the stabilization of HIF1α to promote tumor growth and immunosuppression." (PMID 37350973, 2023). "Under hypoxic conditions, which typically occur in the tumor microenvironment, the expression of this miRNA in ECs is downregulated by transcription factor HIF1α." (PMID 36845338, 2023). "Collectively, these data demonstrated that HIF-1α/YAP signaling promoted PTC tumor proliferation and regulated glucose/iodine metabolism program in vivo." (PMID 36594102, 2023). "As such, this represents a challenging tumor subgroup for therapeutic intervention, although the introduction of HIF-1α inhibitors offers encouragement in this regard." (PMID 37350578, 2023). "Britannin is a compound that disrupts the interaction between Myc and HIF-1α, reducing the expression of PD-L1 and depressing the proliferation rate of tumor cells." (PMID 37296860, 2023). "PGK1 has established a potential tumor promoting role by boosting the HIF-1α expression to stimulate tumor metastasis in BC." (PMID 36949536, 2023). "HIF-1α during hypoxia induces the PDL-1 (CD274) expression in tumor cells, DCs, TAMs, and MDSCs to support immunosuppressive TIME." (PMID 37275901, 2023). "In solid tumors, tumor hypoxia and HIF‐1α promote the upregulation of adenosine‐producing enzymes, such as CD39/CD73, which can dephosphorylate ATP to adenosine." (PMID 36703877, 2023). "An increasing number of studies show that there are overlaps between the HIF-1α and AhR pathways in terms of the control over biological functions, including tumor progression." (PMID 37305351, 2023). "This anti-tumor activity was further corroborated by down regulation of Rac-1/Cdc42/HIF-1α/DDX3/β-catenin signalling." (PMID 37024613, 2023). "Activation of HIF-1α enhances the tumor microenvironment and improves tumor cell survival and propagation through increased blood vessel formation, aggressiveness, metastasis, and resistance to treatment." (PMID 37972206, 2023). "IHC results corroborated that HIF-1α expression was increased in OSCC tumor tissues compared to that in normal tissues, and it was strongly detected in the cytoplasm of epithelial cells." (PMID 37095487, 2023). "Hypoxia and activation of the hypoxia-inducible-factor 1A (HIF1-A) pathway is a major effector in tumorogenesis, tumor therapy resistance, epithelial to mesenchymal transition, invasion and metastasis." (PMID 37371779, 2023). "Succinate induces polarization of tumor-associated macrophages (TAMs) by activating the SUCNR-1 receptor on macrophage membranes and its downstream PI-3K/Akt-HIF-1α signaling pathway." (PMID 37164974, 2023). "Sarcoma is traditionally considered an immunologically quiet tumor with low tumor mutational burden (1.06 mutations/Mb) and immunosuppressive TME (high levels of hypoxia-inducible factor 1 α (HIF1α), macrophages, neutrophils, and decreased T-cell levels)." (PMID 37007160, 2023). "Intriguingly, these tumor-infiltrating neutrophils up-regulated glycolytic factors and hypoxia-inducible factor 1-alpha (HIF-1α) expression compared to neutrophils from the bone marrow and blood of the same mouse." (PMID 36614196, 2023).
tumor (continued). "These cells induce the production of HIF-1α and form a new tumor microenvironment, the immunosuppressive tumor microenvironment, in which HIF-1α inhibits T-cell infiltration and increases T-cell exhaustion." (PMID 37114130, 2023). "This dose led to a 76% decrease in the expression of HIF-1α mRNA in the tumor samples, and increased apoptosis." (PMID 36846589, 2023). "Overall, these results suggested for the first time an attenuation of TME-promoted β1-integrin/HIF-1α axis by resveratrol treatment, indicating the intracellular mode of action of resveratrol in inducing anti-tumor effect in CRC cells." (PMID 36902421, 2023). "HIF-1α is strongly related to tumor metastasis and angiogenesis, with elevated expression of HIF-1α being an indicator of poor prognosis." (PMID 37434755, 2023). "Hypoxia-inducible factor 1α (HIF-1α) immunostaining revealed areas of tumour cells under hypoxic conditions particularly in regions of abnormal vasculature." (PMID 37324244, 2023). "DRD2 was reported to promote malignant tumor progression by activating the oxygen-independent hypoxia-inducible factor-1α (HIF-1α) pathway in response to psychologic stress." (PMID 37584707, 2023). "We have examined tumor tissue expression of HIF-1α in the Group 1 according to clinical tumor characteristics using unpaired t-test." (PMID 38273861, 2023). "A recent study proposed a calcium peroxide-modified magnetic nanoparticle (CaO2-MNPs) which releases oxygen at tumor sites and induces ubiquitin-mediated degradation of HIF-1α." (PMID 37460927, 2023). "Tumor cells easily form a local hypoxic microenvironment owing to their rapid growth, resulting in increased expression of hypoxia-inducible factor-1 alpha (HIF-1α)." (PMID 37864196, 2023). "RP11‐367G18.1 variant 2 was upregulated by hypoxia and HIF‐1α that mediated HIF‐1α‐induced tumor growth and metastasis." (PMID 36847128, 2023). "In early stage glottic LSCC treated with primary radiotherapy, expression of hypoxia (HIF-1α and CA-IX) and proliferation (Ki-67) tumour markers showed prognostic value for local control." (PMID 37029804, 2023). "High lactate levels produced by tumor cells also evoke HIF-1a and HIF-2a accumulation in macrophages, which changes the pro-inflammatory environment to an anti-inflammatory environment by reducing NF-kB activity, in turn reducing T and NK-cell activation." (PMID 36816959, 2023). "VEGFα and HIF-1α play crucial functions in tumor angiogenesis; HIF-1α can boost the mRNA stability of VEGFα and augment the transcriptional activity of VEGFα during hypoxia." (PMID 37476182, 2023). "EPAS1 shares 48% identity with HIF-1α whose regulatory functions in glucose metabolism, cell proliferation, angiogenesis, tumor invasion, and survival have been elucidated over the past decades." (PMID 37124944, 2023). "The upregulation of HIF-1α under hypoxia is a major driver of tumor progression and contributes to tumor growth, metastasis, and resistance to therapy." (PMID 37626752, 2023). "In such manner, studies were conducted in which IL-1α was shown to be regulated by HIF-1α, and a change in HIF-1α expression altered the tumor-promoting effect of IL-1α." (PMID 37007020, 2023). "HIF-1α is an important mediator of the tumor cell response to hypoxia, therefore, identification of HIF1α-regulating network would help the diagnosis and therapy of OS." (PMID 36864422, 2023). "LncRNA VCAN-AS1 has been reported to promote the malignant tumor behaviors via modulating the miR-106a-5p-involved STAT3/HIF-1α axis in breast cancer." (PMID 37696973, 2023). "In the GSE107943 database, we also found that HIF-1a was significantly highly upregulated in tumour tissues compared with normal tissues." (PMID 37821935, 2023). "Many studies have demonstrated the involvement of lncRNAs via HIF-1α regulation in the effects of hypoxic conditions on tumor biological behavior." (PMID 37946265, 2023).